XBP1 (X-box binding protein 1)
Diseases named in the same sentence as XBP1 in open-access papers (continued):
Sharing a sentence is not in itself a finding about the gene and the disease.
keloid (2 papers, 2022 to 2025). An irregularly shaped, elevated mark on the skin caused by deposits of excessive amounts of collagen during wound healing. "Overexpression of RCN1 activates ER stress by regulating IRE1α‐XBP1 pathway and promoting keloid formation." (PMID 40214031, 2025). "The results of Western blotting indicated that the protein expression of ALKBH5, RCN1, IRE1α, and XBP1 were increased in skin tissues of keloid mice, and knockdown of RCN1 reversed the changes." (PMID 40214031, 2025). "Another study suggested that the inhibition of IRE1α also decreased keloid formation and decreased XBP1." (PMID 40214031, 2025). "In this study, we demonstrated that ALKBH5 inhibits YTHDF2‐m6A‐mediated degradation of RCN1 mRNA to promote keloid formation by activating IRE1α‐XBP1‐mediated ER stress." (PMID 40214031, 2025). "Pathway analysis suggested that the XBP1‐mediated unfolded protein response (UPR) pathway was involved in keloid formation." (PMID 35435317, 2022). "Our study proposed four novel biomarkers and highlighted the role of XBP1‐mediated UPR pathway in the pathology of keloids." (PMID 35435317, 2022). "It seems that XBP1 plays an important role in keloid formation because most of the upregulated proteins were shown to be related with XBP1." (PMID 35435317, 2022). "Our data revealed that RCN1 was upregulated by ALKBH5 to promote keloid formation by activating IRE1α‐XBP1‐mediated ER stress, RCN1 may be a potential biomarker for treatment of keloid." (PMID 40214031, 2025). "Prior report indicated that XBP1 was upregulated in keloid tissues." (PMID 40214031, 2025). "In addition, IRE1α‐XBP1 was one of the pathways of ER stress and played a key role in keloid development." (PMID 40214031, 2025). "Moreover, overexpression of RCN1 significantly upregulated the protein levels of XBP1, GRP78, and IRE1α, and promoted ER stress in keloid fibroblasts, but this change was eliminated by sh‐XBP1 intervention." (PMID 40214031, 2025). "Moreover, a previous study showed that XBP1 was upregulated in keloid and IRE1α/XBP1 pathway was activated in keloid fibroblasts." (PMID 40214031, 2025). "We proposed that the XBP1‐mediated UPR pathway plays a role in keloid formation." (PMID 35435317, 2022). "The upregulated expression level of XBP1 in keloids was further verified by WB." (PMID 35435317, 2022).
kidney damage (2 papers, 2023 to 2024). "Compared with the control, XBP1 inhibition in Xbp1+/− mice reduced IR-induced kidney damage and histological scores (0.95 ± 0.21 vs. 3.75 ± 0.35, P < 0.01), and serum creatinine (191.70 ± 5.04 vs. 97.33 ± 10.17, P < 0.01) and blood urea nitrogen levels (68.27 ± 0.64 vs. 47.86 ± 0.64, P < 0.0001)." (PMID 36801911, 2023).
liver failure (2 papers, 2017 to 2019). A liver disease characterized by the liver losing or has lost all of its function. "However, the reported IRE1-knockout phenotype is different from that of XBP1 knockouts in mice: whereas the developmental lethality of XBP1-knockout embryos has been attributed to liver failure, the lethality of IRE1α-knockout mice is attributed to a different organ – specifically, the placenta." (PMID 28775151, 2017).
lung squamous cell carcinoma (2 papers, 2023). "The AGR2 mRNA levels were negatively correlated with XBP1 protein levels in HCC (Spearman: − 0.169, p value: 0.02) in the TCGA, Pancancer microarray dataset and in lung squamous cell carcinoma (Spearman: − 0.16, p value: 3.65e-3)." (PMID 36899352, 2023).
lymph node metastasis (2 papers, 2020 to 2021). "we confirmed that XBP1 was significantly increased in NSCLC tumor tissue and cell lines, and overexpresses XBP1 was associated with TNM stages and lymph node metastasis in NSCLC and the expression of XBP1 was related with the 3-year OS." (PMID 34094948, 2021). "Both XBP1-positive expression and NAT1-negative expression were significantly correlated to poorly differentiated types, advanced TNM stages, lymph node metastasis, invasion, and only receiving biopsy in SC/ASC (all P < 0.05)." (PMID 32793479, 2020). "The percentage of XBP1-positive and NAT1-negative expression was significantly higher in the cases with poor differentiation, advanced tumor, nodes, and metastases (TNM) stage, lymph node metastasis, invasion, and only receiving biopsy in GBC, SC/ASC, and AC (all P < 0.05)." (PMID 32793479, 2020). "Both positive XBP1 expression and negative NAT1 expression were significantly associated with the poorly differentiated type, larger tumor size (>3 cm), advanced TNM stage (III + IV), lymph node metastasis, invasion, and only receiving biopsy in GBC (all P < 0.05)." (PMID 32793479, 2020).
meningioma (2 papers, 2022 to 2025). A generally slow growing tumor attached to the dura mater. "The odds ratios (ORs) of these genes were significantly high, indicating a positive causal relationship with meningiomas (TRPC6: ORIVW = 2.11; XBP1: ORIVW = 1.40; TTC28: ORIVW = 1.93 and ODF3: ORWald ratio = 4.76)." (PMID 40046334, 2025). "The results indicated that the expression of these four genes is causally stable in meningiomas (TRPC6: PIVW = 1.09×10−7; XBP1: PIVW = 4.28×10−11; TTC28: PIVW = 7.92×10−5; ODF3: PWald ratio = 7.94×10−8)." (PMID 40046334, 2025). "XBP1 showed the highest upregulation in macrophages from patients with meningioma compared with that in healthy individuals, with some upregulation in monocytes, tissue stem cells and NK (natural killer) cells." (PMID 40046334, 2025). "For example, XBP1 was downregulated in B and NK cells from patients with meningioma compared with that in healthy individuals, whereas its expression level in macrophages and monocytes was upregulated in patients with meningioma." (PMID 40046334, 2025). "Our study is the first to identify the high expression of XBP1 in meningioma, which may facilitate further exploration of meningioma-targeted drugs." (PMID 40046334, 2025). "In the context of meningioma, XBP1’s upregulation suggests that tumour cells may rely on the UPR to cope with increased protein synthesis and misfolding, conditions typical in rapidly growing tumours." (PMID 40046334, 2025). "Moreover, our Ingenuity Pathway Analysis revealed that the transcription factors ATF3, ATF4, ATF6, and XBP1 were activated in meningioma cells exposed to DSF/Cu." (PMID 35453636, 2022). "By extracting specific cells in which the four prioritized genes were expressed, we validated the high expression of XBP1, TTC28 and TRPC6 in meningioma tissues." (PMID 40046334, 2025). "We focused on differences in the expression of the four identified genes (XBP1, TTC28, TRPC6 and ODF3) between meningioma and normal brain tissues." (PMID 40046334, 2025). "In this study, we performed SMR, colocalization and MR analyses using meningioma summary statistics from FinnGen r9 and eQTL data from eQTLGen, and identified XBP1, TTC28, TRPC6 and ODF3 as potential therapeutic gene targets for meningioma." (PMID 40046334, 2025). "In conclusion, the identification and validation of TRPC6, XBP1 and TTC28 as potential targets for meningioma therapy represent a significant advancement in our understanding of the disease and open new avenues for therapeutic interventions." (PMID 40046334, 2025). "The integration of bulk and single-cell RNA sequencing confirmed the upregulated expression of three of the genes (XBP1, TTC28 and TRPC6) in meningioma tissues, unravelling their cellular distribution and hinting at the tumour’s intrinsic heterogeneity." (PMID 40046334, 2025).
Metaphyseal chondrodysplasia, Schmid type (2 papers, 2019 to 2022). "Paradoxically, this is in direct contrast to the minor role for XBP1 signalling proposed in the recent study of the Col10aN617K model of metaphyseal chondrodysplasia type Schmid (MCDS)." (PMID 31260448, 2019). "A similar upregulation of XBP1 signalling was seen in the Col10a1 N617K model of metaphyseal chondrodysplasia type Schmid (MCDS), but not in an allelic series of pseudoachondroplasia (PSACH) causing Comp mutations, indicating gene product specificity of this arm of the UPR." (PMID 31260448, 2019).
metastatic cancer (2 papers, 2022 to 2026). A carcinoma which has spread from the original site of growth to another anatomic site. "During metastasis, the IRE1α-XBP1 pathway interacts with HIF1α (Hypoxia-inducible factor 1-alpha) to promote tumor growth and survival in hypoxia, making it a potential target for treating metastatic cancer." (PMID 41346768, 2026).
multiple epiphyseal dysplasia (2 papers, 2011 to 2019). Multiple epiphyseal dysplasias (MED/EDMs) are characterized by epiphyseal anomalies causing joint pain early in life, recurrent osteochondritis and early arthrosis. "It remains unknown whether Xbp1 splicing, Atf6 proteolysis, or Eif2α phosphorylation occur in other mouse models of skeletal dysplasias characterized by ER stress, including the p.V194D Matn3 mutant model of multiple epiphyseal dysplasia, and an Aga2-mutant model of osteogenesis imperfecta." (PMID 21935428, 2011).
neutropenia (2 papers, 2022 to 2025). A decrease in the number of neutrophils found in the blood. "Loss of Xbp1 in the zebrafish also shows a similar neutropenia phenotype, consistent with this being a key driver of the disease phenotype." (PMID 35409131, 2022). "The heterogenic phenotypes of SDS-like disease and mild to severe neutropenia observed in patients with SRP54 variants may be the result of the effect that mutant SRP54 proteins exert on downstream XBP1 splicing in a dominant-negative manner." (PMID 41383606, 2025). "Furthermore, the neutropenia phenotype has been linked to impaired splicing of the XBP1 transcription factor required for the unfolded protein response and which is spliced in an unconventional manner by IRE1 following its membrane targeting by SRP." (PMID 35409131, 2022).
optic neuropathies (2 papers, 2017 to 2018). "As in traumatic and glaucomatous optic neuropathies, eIF2α-CHOP inhibition and XBP-1 activation preserve the morphology and function of both RGC somata and axons after inflammatory demyelination of ON." (PMID 28726788, 2017).
osteogenesis imperfecta (2 papers, 2011 to 2018). Osteogenesis imperfecta (OI) comprises a heterogeneous group of genetic disorders characterized by increased bone fragility, low bone mass, and susceptibility to bone fractures with variable severity. "Such a possibility is consistent with another report where a osteogenesis imperfecta COL1A2 G610C mutation causes procollagen I misfolding in the ER of osteoblasts and abnormal osteoblast differentiation, but did not induce the classical UPR mediators BiP or Xbp1-spliced form." (PMID 30024379, 2018).
parasitemia (2 papers, 2016 to 2021). "Despite the absence of follicles, a rapid accumulation of Aicda+ GC-like B cells followed first parasitemia peak clearance, accompanied by the occurrence of Xbp1+ expressing CD138+ plasma B cells and Tbx21+ atypical CD11c+ memory B cells." (PMID 34762705, 2021). "These investigations would include determining the role of XBP-1 in resistance to oxidative stress due to Leishmania infection and examining other components of the ER stress signaling pathway, such as ATF6, in the context of parasitic infection." (PMID 27499755, 2016).
polycystic kidney (2 papers, 2021 to 2022). "Double knockout of Sec63 and Xbp1 enhances the severity of polycystic kidney disease in mice and re-expression of XBP1s is able to rescue the inactivation of Sec63 with XBP1 or IRE1α induced interstitial inflammation and fibrosis." (PMID 35765067, 2022). "Double knockout of SEC63 and XBP-1 worsens the polycystic kidney phenotype, whereas overexpression of XBP-1 in distal tubules in SEC63-deletion mice attenuates cyst formation through enhanced biogenesis of PC-1." (PMID 33671535, 2021).
subarachnoid hemorrhage (2 papers, 2019 to 2023). A serious neurological disorder characterized by intracranial hemorrhage into the subarachnoid space. "IRE1/XBP1 branch is a new idea to regulate protein glycosylation modification, and provides a promising strategy for clinical perioperative prevention and treatment of subarachnoid hemorrhage." (PMID 37238930, 2023).
Achalasia (1 paper, 2016). A disorder of esophageal motility characterized by the inability of the lower esophageal sphincter to relax during swallowing and by inadequate or lacking peristalsis in the lower half of the body of the esophagus. "Interestingly, in our results, IRF4 and BLIMP1 are important upstream regulators of genes down-regulated, such as XBP1, IGHM, CD79A, RORC, and IKZF2, stressing the implications of the immune-inflammation network in achalasia." (PMID 27511445, 2016).
acute monocytic leukemia (1 paper, 2012). Acute monoblastic leukemia (AML-M5), is one of the most common subtypes of acute myeloid leukemia (AML) that is either comprised of more than 80% of monoblasts (AML-M5a) or 30-80% monoblasts with (pro)monocytic differentiation (AML-M5b). "A similar method was recently employed to demonstrate the quantitative changes of IRE1-dependent XBP-1 processing in Caenorhabditis elegans upon infection with Pseudomonas aeruginosa and in a human acute monocytic leukemia cell line." (PMID 22359644, 2012).
adenosquamous carcinoma (1 paper, 2020). A carcinoma composed of malignant glandular cells and malignant squamous cells. "Then, we assayed XBP1 and NAT1 expression in 215 GBCs, including 69 squamous cell/adenosquamous carcinomas (SC/ASCs) and 146 adenocarcinomas (ACs) with immunohistochemistry." (PMID 32793479, 2020).
adenovirus infection (1 paper, 2020). "To investigate whether NF-κB activation is regulated by XBP1 through IKK, we determined the effect of XBP1 on FFA-induced phosphorylation of IKK by overexpression of XBP1 via adenovirus infection." (PMID 31630283, 2020).
airway allergy (1 paper, 2022). "The data suggest that inhibiting XBP1 has the translation potential for the treatment of airway allergy." (PMID 35910793, 2022). "In other words, the current study identified that RhoA was also a potential therapeutic target for airway allergy in addition to XBP1." (PMID 35910793, 2022). "Blocking XBP1 or RhoA can inhibit experimental airway allergy, suggesting that blocking RhoA or XBP1 has translation potential for treating airway allergy." (PMID 35910793, 2022). "The data suggest that XBP1 and RhoA are potential new targets for the treatment of airway allergy." (PMID 35910793, 2022). "In this study, we found that the ablation of XBP1 prevented the development of airway allergy." (PMID 35910793, 2022). "The results indicate that XBP1 may be a therapeutic target for the treatment of airway allergies." (PMID 35910793, 2022). "The inhibition of either Etr or RhoA, or the depletion of XBP1 in CD4+ T cells, prevented the induction of airway allergy using the MNP.Derf1 protocol." (PMID 35910793, 2022). "This study identified a new therapeutic target, XBP1 in CD4+ T cells, for airway allergy." (PMID 35910793, 2022).
alcoholic pancreatitis (1 paper, 2022). Acute or chronic inflammation of the pancreas due to excessive alcohol drinking. "In a mouse model for alcoholic pancreatitis, alcohol exposure activated IRE1/Xbp1-mediated UPR and only caused minimal pancreas damage in WT mice." (PMID 35052788, 2022).
anaphylaxis (1 paper, 2023). An acute hypersensitivity reaction that occurs from exposure to an allergen. "Additional evidence is documented suggesting that IRE1 RNAase activity may lead to activation of spleen tyrosine kinase (SYK) as inhibition of the RNAase domain reduced both XBP1 and SYK activation in a mouse model of anaphylaxis." (PMID 37107600, 2023).
Atherosclerotic lesion (1 paper, 2021). A lesion associated with atherosclerosis, a multifactorial and multipart progressive disease manifested by the focal development within the arterial wall of lesions, that ranges from the development of a fatty streak, plaque progression, and plaque disruption. "Downregulation of miR-512-3p enhanced the viability, suppressed the apoptosis, and promoted the migration of ox-LDL-treated HUVECs, alleviated atherosclerotic lesions in AS model mice as well as repressed autophagy and ER stress by targeting XBP-1 to manipulate the ratio of XBP-1S/XBP-1 U." (PMID 34783632, 2021).
bone tumors (1 paper, 2018). "Taqman RT PCR analysis of PC3 bone tumors revealed significantly higher levels of BIP and XBP1." (PMID 29311669, 2018).
cardiomyopathy (1 paper, 2023). A disease of the heart muscle or myocardium proper. "Xbp1 expression, a sarcoplasmic reticulum stress-responsive transcription factor, enhances the stress-responsive capacity of the sarcoplasmic reticulum and rescues cardiomyopathy caused by mitofusin/MARF deficiency without ameliorating cardiomyopathy caused by Opa1 deletion." (PMID 37895224, 2023).
cartilage disorders (1 paper, 2025). "A regulatory network involving LncRNA/circRNA-miRNA interactions in Xbp1-deficient chondrocytes offers potential therapeutic targets for cartilage disorders." (PMID 41301756, 2025).
Cerebral atrophy (1 paper, 2022). Atrophy (wasting, decrease in size of cells or tissue) affecting the cerebrum. "Intuitively, cerebral atrophy was the mildest in the lesion side of the ov-Xbp1 group, followed by the the NC and sh-Xbp1 groups." (PMID 36348288, 2022).
Chlamydia infection (1 paper, 2016). "Furthermore, we found that Chlamydia infection-induced IRE1α activation was dependent on TLR4 signalling as XBP-1 splicing was reduced in the presence of a TLR4 blocking antibody, and similar results were obtained with LPS as a control." (PMID 27021640, 2016).
Cholestatic liver disease (1 paper, 2022). "We evaluated hepatic UPR expression in pediatric cholestatic liver disease (CLD) explants and hypothesize that an inability to appropriately activate the hepatic IRE1α/XBP1 pathway is associated with the pathogenesis of CLD." (PMID 36520816, 2022). "This study identified that hepatic gene and protein expression of IRE1α/XBP1 signaling and other UPR signaling differs in progressive cholestatic liver diseases compared to normal controls and therefore may be important in the pathogenesis of disease." (PMID 36520816, 2022).
chordoma (1 paper, 2019). Chordomas are rare malignant tumors arising from embryonic remnants of the notochord in axial skeleton. "In this study, we find that Doxo or Irino induce a moderate UPR in chordoma cells as shown by an increased expression of CHOP, BiP, ATF4, ATF6, and XBP1-s." (PMID 31767864, 2019).
Chronic colitis (1 paper, 2024). A chronic inflammatory disease of the large intestine (colon, cecum and rectum). "Here, we demonstrate that IRE1α/XBP1 strengthens IL-23 signaling in ILC3s, enhancing protection against both acute and chronic colitis in mice." (PMID 38722686, 2024).
chronic rhinosinusitis (1 paper, 2022). Chronic form of sinusitis. "This study was performed to characterize the function of XBP1, which was identified to be a differentially expressed gene via GEO database, in chronic rhinosinusitis (CRS) without nasal polyps (CRSsNP)." (PMID 35915851, 2022).
cognitive decline (1 paper, 2024). "Preoperative administration of TUDCA downregulated the expression of GRP78 and XBP1 and inhibited NLRP3 inflammasome activation and neuroinflammation, thereby exhibiting an obvious therapeutic effect against postoperative cognitive decline." (PMID 39432407, 2024).
cutaneous leishmaniasis (1 paper, 2017). Leishmaniasis affecting the skin. "To address the clinical relevance of our in vitro mechanistic data, we assayed expression of ATF4, XBP-1 and HO-1 in clinical samples obtained from patients with cutaneous leishmaniasis." (PMID 29213084, 2017).